HJURP (Holliday junction recognition protein)
Diseases named in the same sentence as HJURP in open-access papers (continued):
Sharing a sentence is not in itself a finding about the gene and the disease.
hepatocellular carcinoma (17 papers, 2016 to 2025). A malignant tumor that arises from hepatocytes. "Hypomethylation-driven overexpression of HJURP promotes the progression of hepatocellular carcinoma (HCC) and is associated with poor prognosis." (PMID 40290723, 2025). "Among them, TYMS, KIF2C, UBE2C, and HJURP are associated with unfavorable prognosis in hepatocellular carcinoma, possibly due to the malignant growth of cells." (PMID 37035748, 2023). "We and others have shown that the Holliday cross-recognition protein HJURP can promote the proliferation, migration, and invasion by hepatocellular carcinoma cells, and that HJURP overexpression is associated with poor survival." (PMID 35783358, 2022). "Moreover, HJURP has been linked to poor prognosis in various cancers, including non-small cell lung cancer, hepatocellular carcinoma, and renal cell carcinoma." (PMID 40299539, 2025). "Several studies based on clinical tumor samples also confirmed the risk of HJURP to the tumorigenesis or development of cholangiocarcinoma, colorectal cancer, pancreatic cancer, triple-negative breast cancer and hepatocellular carcinoma." (PMID 39649097, 2024). "Holliday junction recognition protein (HJURP) has been implicated in many cancers including hepatocellular carcinoma (HCC)." (PMID 30111352, 2018). "Aberrant HJURP expression is common in tumors, including hepatocellular carcinoma, renal cell carcinoma, ovarian cancer, osteosarcoma, pancreatic cancer, and oral cancer." (PMID 37025176, 2023). "Several studies have shown that HJURP expression is significantly upregulated in hepatocellular carcinoma (HCC) tissues compared to paraneoplastic tissues." (PMID 37025176, 2023). "As revealed by the promoter methylation status chart, HJURP was hypomethylated in bladder urothelial carcinoma, renal papillary cell carcinoma, hepatocellular carcinoma, prostate cancer and testicular germ cell carcinoma, etc.." (PMID 36460821, 2022). "As for cancer progression, HJURP was reported to promote progression in several cancer types including hepatocellular carcinoma, prostate cancer, pancreatic cancer, and glioblastoma." (PMID 35965590, 2022). "Here we explored the potential relationship between HJURP and the tumor microenvironment in hepatocellular carcinoma." (PMID 35783358, 2022). "We examined whether the single nucleotide polymorphisms (SNPs) of HJURP were associated with the risk of occurrence of hepatocellular carcinoma (HCC) among chronic hepatitis B virus (HBV) carriers from well-known high-risk regions for HCC in China." (PMID 26863619, 2016). "Interestingly, immunohistochemical assays indicated that HJURP localized mainly in the cytoplasm in both prostate cancer and hepatocellular carcinoma cells." (PMID 37025176, 2023). "In line with our findings, HJURP expression has been reported in prostate cancer to be predominantly cytoplasmic, the hepatocellular carcinomas also display a cytoplasmic expression, whereas in gliomas, HJURP immunoreactivity is observed both in the nucleus and in the cytoplasm." (PMID 35955489, 2022). "A comprehensive analysis in hepatocellular carcinoma revealed that ASF1A and HJURP serve as a two-gene prognostic model due to their involvement in H3-H4 histone chaperone functions." (PMID 40290723, 2025). "Based on single-cell RNA sequencing, HJURP was strongly expressed in T cells, erythrocytes, and B cells from normal liver tissues, as well as in CD8+ T cells, dendritic cells, and one cluster of hepatocytes in hepatocellular carcinoma tissues." (PMID 35783358, 2022). "We used a normal hepatocyte-derived cell line (LO2) as the control and compared the relative expression levels of ASF1A and HJURP in LO2 and five hepatocellular carcinoma (HCC) cell lines (Hep3B, Huh-7, LM3, SNU-368, SNU-739) using qRT‒PCR) and WB experiments." (PMID 38561384, 2024).
prostate carcinoma (17 papers, 2020 to 2026). A carcinoma that arises from epithelial cells of the prostate gland. "High tumor mutation burden in HJURP and other genes in prostate cancer is associated with greater activation of memory CD4+ T cells." (PMID 35783358, 2022). "PRDX1 (Peroxiredoxin 1) is a widely expressed peroxidase, and in prostate cancer, HJURP may inhibit tumor cell sensitivity to iron mutation inducers via the PRDX1 pathway." (PMID 41523581, 2026). "Importantly, nuclear HJURP positivity was associated with advanced T-status, in accordance with previous investigations in other tumors, such as in lung, kidney, prostate carcinoma and cholangiocarcinoma." (PMID 39200236, 2024). "We identified a novel gene risk panel comprising six genes (SSTR1, CA14, HJURP, KRTAP5-1, VGF, and COMP) for prostate cancer risk classification." (PMID 40592939, 2025). "In prostate cancer, HJURP increased the ubiquitination of cyclin-dependent kinase inhibitor one via the GSK3β/JNK signaling pathway, decreasing its stability and thereby promoting cell proliferation." (PMID 39649097, 2024). "CENPF is related to cellular proliferation and mitotic activity, driving prostate cancer metastasis, while HJURP is involved in regulating the centromeric deposition of CENPF and controls cell cycle progression." (PMID 36245556, 2022). "Increased HJURP expression has been correlated advanced with tumor stage in prostate cancer and ovarian adenocarcinoma, whilst increased CENP-A expression has been associated with advanced tumor stage in lung and ovarian adenocarcinomas." (PMID 35955489, 2022). "Here, we found a total of 137 genes were ectopically expressed in eight cancer types, of which Holliday junction recognition protein (HJURP) was significantly upregulated in prostate cancer (PCa)." (PMID 34099634, 2021). "It is thus conceivable that either HJURP or DAXX carries out a chaperone like function for CENPA in prostate cancer, although re-ChIP assays involving CENPA and HJURP together or CENPA and DAXX together would be necessary to prove the presence of such a mechanism." (PMID 32371391, 2020). "HJURP increased the ubiquitination of CDKN1A via the GSK3β/JNK signaling pathway and decreased its stability, thus promoting prostate cancer cell proliferation." (PMID 35459269, 2022). "Indeed, our data show that HJURP, the chaperone that directs CENPA to centromeric DNA, demonstrates strong concordance with CENPA expression in prostate cancer tissue." (PMID 32371391, 2020).
lung carcinoma (15 papers, 2009 to 2024). "In PrognoScan, HJURP expression was remarkably linked to five kinds of cancers, consisting of blood, brain, breast, soft tissue, and lung cancer." (PMID 35274047, 2022). "HJURP is an important factor promoting the immortalization of cancer cells and is associated with poor prognosis in lung cancer patients." (PMID 36712848, 2022). "Still, whether detection of HJURP in plasma might aid the diagnosis of lung cancer, and the potential involvement of HJURP in tumor-associated immune infiltration, are topics worth of further investigation." (PMID 37025176, 2023). "In single-cell sequencing data based on lung cancer tissues, HJURP was significantly more highly expressed in malignant cells compared to immune cells and stromal cells (p < 0.001)." (PMID 39649097, 2024). "The study, which included 47 lung cancer patients and 14 healthy subjects, showed that the expression of HJURP was significantly upregulated in lung cancer patients." (PMID 37025176, 2023). "At the optimal cut-off point, plasma HJURP separated lung cancer patients from healthy individuals with a sensitivity of 66.0%, a specificity of 78.6%, and an AUC (area under the ROC) of 0.696." (PMID 37025176, 2023). "What is more, cell-free mRNAs of Holliday junction recognition protein (HJURP) were found to be expressed at significant levels in plasma from patients with lung cancer." (PMID 35884419, 2022). "HJURP has been demonstrated to be correlated with multiple human neoplasms, including bladder, breast, liver, and lung cancer, as well as glioma." (PMID 32439850, 2020). "Like most other histone chaperones, the overexpression of HJURP has been observed in multiple cancers, such as bladder cancer, breast cancer, liver cancer, and lung cancer, as well as glioma." (PMID 32439850, 2020). "Holliday Junction Recognition Protein (HJURP, also known as hFLEG1), which is a newly discovered gene, was reported to be overexpressed in lung cancer cells through genome-wide expression profile analysis." (PMID 20211017, 2010). "It was demonstrated that HJURP is over expressed in lung cancer and is involved in chromosomal stability, being a competence factor for immortality of cancer cells in culture." (PMID 19257903, 2009). "Moreover, HJURP expression was closely related to smoking status, with higher expression observed in current and ever smokers with lung cancer (TCGA-LUAD: p < 0.001, GSE31210: p < 0.001), suggesting that smoking may influence tumorigenesis by upregulating HJURP expression." (PMID 39649097, 2024). "Our decision to focus on HJURP stems from its well-documented function in maintaining chromosomal stability through the centromeric loading of CENP-A, a key process that is often dysregulated in various cancers, including lung cancer." (PMID 39649097, 2024). "As expected, IHC staining revealed that protein expressions of FOXM1, HJURP, and PTTG1 were all significantly elevated in tumors compared with adjacent normal tissues, indicating that SRS genes may play an important in lung cancer progression." (PMID 34869385, 2021).
glioblastoma (10 papers, 2009 to 2025). The most malignant astrocytic tumor (WHO grade IV). "Additionally, modulation of HJURP levels has been linked to glioblastoma cell survival." (PMID 40290723, 2025). "Reducing HJURP levels disrupts clonogenic capacity and increases radiation-induced cell death in glioblastoma cells." (PMID 40290723, 2025). "For instance, suppression of HJURP induced cell senescence and abolished cell-cycle dynamics in glioblastoma." (PMID 35459269, 2022). "In this context, we previously demonstrated that HJURP, a novel protein involved in the repair of DNA double-strand breaks, is highly overexpressed in glioblastoma." (PMID 23638004, 2013). "To investigate the role of HJURP in glioblastoma cells, we performed knockdown experiments using double-stranded synthetic RNA oligonucleotides (siRNAs) directed to the coding region of HJURP mRNA." (PMID 23638004, 2013). "We also observed that HJURP knockdown strongly affects the maintenance of glioblastoma cells in a selective manner." (PMID 23638004, 2013). "More importantly, we found that HJURP knockdown strongly affects the maintenance of glioblastoma cells in a selective manner." (PMID 23638004, 2013). "HJURP knockdown increases radiation-induced apoptosis in glioblastoma cells." (PMID 36105094, 2022). "We previously demonstrated that HJURP is highly over expressed in glioblastoma multiforme." (PMID 23638004, 2013). "Additionally it was observed that the expression level of HJURP in glioblastoma was changed about nine fold compared to typically benign pilocytic astrocytomas by microarray profile analysis." (PMID 20211017, 2010). "The role of HJURP in glioblastoma will be further characterized." (PMID 19257903, 2009). "In glioblastoma (GBM), HJURP is often overexpressed, and the knockdown of HJURP disrupts the colony-forming ability of GBM cells and increases their radio sensitivity." (PMID 36941564, 2023). "Immunohistochemical staining for EDN/RB, HJURP, p60/CAF-1 and PDLI4 was studied on archive materials from 96 patients (64 glioblastomas and 32 grade III gliomas)." (PMID 24039914, 2013). "The expression of EDNRB, HJURP and PDLIM4 genes were significantly different between glioblastomas and grade III gliomas (p<0.001, p=0.004 and p<0.001, respectively)." (PMID 24039914, 2013). "However, the percentage of displaying positive staining was significantly higher in glioblastomas than in grade III gliomas, for all the proteins tested (EDN/RB: p<0.001, p60/CAF-1: p<0.001, PDLI4: p=0.007 and HJURP: p<0.005)." (PMID 24039914, 2013). "Furthermore, we demonstrated that HJURP knockdown in different cell lines significantly affected the survival of glioblastoma cells but did not impact non-tumoral cells." (PMID 23638004, 2013). "We evaluated the levels of the EDN/RB, HJURP, p60/CAF-1 and PDLI4 proteins by immunohistochemistry in six adult brain samples, four foetal brain samples and 96 high-grade glioma samples, including 64 glioblastomas (grade IV) and 32 grade III gliomas (24 AA and 8 AO)." (PMID 24039914, 2013).
glioma (9 papers, 2013 to 2024). A benign or malignant brain and spinal cord tumor that arises from glial cells (astrocytes, oligodendrocytes, ependymal cells). "A meta-analysis incorporating four public repositories and datasets (REMBRANDT, TCGA, GSE4271, and GSE4412) showed an association between high HJURP expression and poorer survival prognosis in glioma patients." (PMID 37025176, 2023). "HJURP over expression was also included in a 4-gene signature associated with poor clinical outcome of high-grade malignancy gliomas." (PMID 23638004, 2013). "Thus, the impact of HJURP on glioma progression may be related to the loss of CENP-A from the centromere, with subsequent deficiency in the maintenance of post-mitotic centromeric structure." (PMID 37025176, 2023). "Silencing of HJURP in glioma cells resulted in prominent morphological changes paralleled by significantly decreased viability, increased apoptosis, cell cycle arrest in the G2/M phase, and accelerated senescence." (PMID 37025176, 2023). "We have shown here that HJURP is highly over expressed in different grade gliomas encompassing low-grade diffuse and anaplastic astrocytomas, and GBMs." (PMID 23638004, 2013). "Further experiments must be done to investigate the function of HJURP in the radioresistance of glioma cells." (PMID 23638004, 2013). "In glioma, HJURP has been detected in both the cytoplasm and nucleus." (PMID 39405980, 2024). "Interestingly, and contrasting with the effect observed in BC cells, HJURP silencing increased radiotherapy-induced death in glioma cell lines." (PMID 37025176, 2023). "Meanwhile, HJURP expression was detected in both the cytoplasm and nucleus of gliomas." (PMID 37025176, 2023). "It was thus concluded that KLF11 promotes the progression of glioma through positive regulation of HJURP, and that both proteins could be used as biomarkers for glioma diagnosis and prognosis." (PMID 37025176, 2023). "HJURP is a histone chaperone shown to play a role in the progression of gliomas and breast tumors." (PMID 28454104, 2017). "Altogether, these data suggest that the high levels of HJURP might have an essential function for survival of the extremely proliferative cells of high-grade malignancy gliomas and points out HJURP as a potential novel therapeutic target." (PMID 23638004, 2013). "Coupled to artificial overexpressed CENP-A, which results in ectopic or non-centromeric CENP-A localization, overexpression of its chaperone HJURP also correlates with disease prognosis in gliomas, although it is unknown if overexpressed HJURP drives ectopic CENP-A localization." (PMID 26262644, 2015). "Mean levels of the EDN/RB, HJURP, p60/CAF-1 and PDLI4 proteins were found to be significantly higher in grade IV gliomas than in grade III gliomas." (PMID 24039914, 2013). "The expression of the EDN/RB, HJURP, p60/CAF-1 and PDLI4 proteins is disrupted in high grade gliomas and increases in the levels of these proteins are closely linked to tumour aggressiveness and poor outcome." (PMID 24039914, 2013).
pancreatic cancer (9 papers, 2017 to 2025). "In addition, we also analyzed the ROC curves of HJURP in pancreatic cancer patients and healthy controls (AUC = 0.753, p < 0.05)." (PMID 32439850, 2020).
bladder cancer (6 papers, 2019 to 2025). "Interestingly, the regulation of ROS production by HJURP varies in different kinds of cancer: HJURP inhibits ROS production via the PPARγ-SIRT1 feedback loop in bladder cancer, while it enhances ROS stress in renal cell carcinoma." (PMID 39405980, 2024). "Knockdown experiments provided evidence that HJURP could regulate bladder cancer cell’s proliferation and apoptosis via the PPARγ-SIRT1 negative feedback loop." (PMID 31847118, 2019). "Holliday junction recognition protein (HJURP) is a centromeric histone chaperone that also acts on the PPARγ-SIRT1 negative feedback loop, impacting on cell proliferation and apoptosis in bladder cancer." (PMID 32328200, 2020). "In addition, our group found that HJURP could have an impact on the PPARγ-SIRT1 feedback loop, regulating ROS metabolism, and resulting in the progression of bladder cancer." (PMID 32328200, 2020).
colorectal cancer (6 papers, 2017 to 2025). A primary or metastatic malignant neoplasm that affects the colon or rectum. "HJURP expression is associated with colorectal cancer and has been suggested to be a potential prognostic biomarker and a novel target for drug discovery due to the higher survival rate of patients with high HJURP expression compared to those with low expression." (PMID 34203193, 2021). "To investigate the function of HJURP in the colorectal cancer cell, we suppressed HJURP expression by siRNA and confirmed proliferation, migration, invasion, and anchorage independent of colony forming ability." (PMID 33114545, 2020). "This suggests that the expression of HJURP decreases the survival rate of colorectal cancer patients." (PMID 33114545, 2020). "In this study, we aimed to evaluate the expression of HJURP in 162 colorectal cancer tissue." (PMID 33114545, 2020). "In this study, we conducted a pathologic evaluation of HJURP expression in CRC using immunohistochemistry (IHC), followed by a functional evaluation of HJURP knockdown by siRNA in four colorectal cancer cell lines to investigate prognostic biomarkers." (PMID 33114545, 2020).
multiple myeloma (6 papers, 2022 to 2025). "Studies have demonstrated that in multiple myeloma, super enhancers facilitate the excessive activation of the histone chaperone protein HJURP." (PMID 39838405, 2025). "Suppressing the expression of HJURP or reducing the activity of super enhancers can lead to a reduction in the survival of tumor cells and the initiation of programmed cell death, offering a promising new target for treating multiple myeloma." (PMID 39838405, 2025).
breast tumors (5 papers, 2010 to 2017). "The PR gene, PGR, and 3 other genes (GATA3, STC2 and GLI3) are increased in their expression, whereas the expression of 6 genes (AURKA, BUB1, CDC20, MKI67, HJURP, and CENPA) is decreased in PR-positive breast tumors." (PMID 22022496, 2011).
melanoma (5 papers, 2017 to 2023). A malignant, usually aggressive tumor composed of atypical, neoplastic melanocytes. "The results suggested a correlation between HJURP expression and tumors such as lung adenocarcinoma, melanoma, diffuse large B lymphoma, renal cell carcinoma, and thymic carcinoma, etc., and patients with high HJURP expression had poorer prognosis." (PMID 36460821, 2022).